CD34 (CD34 molecule)
Diseases named in the same sentence as CD34 in open-access papers (continued):
Sharing a sentence is not in itself a finding about the gene and the disease.
adenoma (9 papers, 2009 to 2025). A neoplasm arising from the epithelium. "The co-expression of IL-8RA and IL-8RB with CD34+ tumor-associated microvessels in both the adenoma and CRC or with LGR5 labeled cancer stem-like cells (CSCs) in CRC tissue sections." (PMID 40149674, 2025). "TCs/CD34+ SCs and their processes were observed in the well-defined delimiting region between the adenomas and the peripheral compressed parathyroid gland, and around adenomatous nests and medium- and small-sized vessels contacting this delimiting region." (PMID 37569493, 2023). "In conclusion, TCs/CD34+ SCs are an important stromal cell component in the normal parathyroid glands and participate in pathologic processes such as hyperplasia and adenomas of these glands." (PMID 37569493, 2023). "Results showed that IL-33 immunoreactivity (IR) is observed in diverse cells, including adenoma/CRC cells, CD3 positive lymphocytes, SMA-alpha positive myofibroblasts and CD34 positive endothelial cells of tumor-associated microvessels." (PMID 30547011, 2018). "As many adenomas contain more CD34+ cells, we accordingly observed extensive expression of the PADI4 enzyme in these tissues." (PMID 19183436, 2009). "In this work, we contributed for the first time the location, characteristics, and arrangement of TCs/CD34+ SCs in the adult and developmental parathyroid glands and in their most frequent pathological conditions, including parathyroid hyperplasia and adenomas." (PMID 37569493, 2023). "As illustrated in adenomas, we also found that both IL-33- and ST2-IRs are expressed in CRC cells, CD3 positive lymphocytes, SMA-alpha positive myofibroblasts, and CD34 positive microvessels within the CRC microenvironment." (PMID 30547011, 2018). "TCs/CD34+ SCs are present in delimiting regions with compressed parathyroids and their capsule in adenomas but absent in most adenomatous tissue." (PMID 37569493, 2023). "While CD34 showed diffuse positive staining in HCC but not in normal liver tissue, positive staining in some cases of benign hepatic lesions, such as focal nodular hyperplasia and adenoma, was also noted." (PMID 21338527, 2011).
essential thrombocythemia (9 papers, 2014 to 2024). A chronic myeloproliferative neoplasm that involves primarily the megakaryocytic lineage. "In addition, LYZ could interact with CD34+ cells and neutrophils, which may predict an increased risk of thrombosis in essential thrombocythemia patients." (PMID 33587010, 2021). "IRS2 expression was significantly higher in CD34+ cells from essential thrombocythemia patients compared to healthy donors, and in JAK2V617F MPN patients when compared to JAK2WT." (PMID 26755644, 2016). "We have recently showed that patients with PMF have an increased frequency of circulating CD34+/CD133+/VEGFR2+ cells as compared to the patients with Ph-neg chronic MPNs (Polycythemia Vera, PV and Essential Thrombocythemia, ET) and healthy subjects." (PMID 24603752, 2014).
fibroma (9 papers, 2009 to 2025). A non-metastasizing neoplasm arising from the fibrous tissue. "Calcitonin, inhibin, CD34, and α-glutathione S-transferase (αGST) positivity has been reported to be useful to differentiate sclerosing stromal tumors from thecomas, fibromas and other sex cord stromal tumors." (PMID 23097733, 2012). "In contrast, the spindle cells of sclerotic fibromas are positive for CD34." (PMID 40376352, 2025). "The spindled, pleomorphic and occasional multinucleated stromal cells in the fibrovascular connective tissue that forms the core of fibroepithelial polyps show CD34 expression and in some cases (above all with components resembling pleomorphic fibroma) αSMA expression." (PMID 34298962, 2021). "CD34 stains the endothelium of often dilated and branching vascular architecture and clearly distinguishes SST from thecoma and fibroma." (PMID 23097733, 2012). "Myofibromas/myofibromatosis and fibromas may be highly collagenic, and express vimentin, HHF35 and muscle-specific actin; they are CD34 negative." (PMID 19893953, 2009).
gastric adenocarcinoma (9 papers, 2010 to 2026). "PAS-positive large cuboidal tumor cells (blue arrows) and CD34-positive endothelial cells (red arrow) enclosed a narrow lumen containing one erythrocyte (asterisk) in the tissues from patients with gastric adenocarcinoma." (PMID 30833656, 2019). "By means of immunohistochemical analysis, all GIST cells expressed CD117, CD34 and Dog1 in all six synchronous gastric adenocarcinomas with GIST, and in GIST alone." (PMID 29018259, 2017). "Finally, the potential of the different CEA-4-1BBL antibody fusion proteins as signal 2 providers in combination with CEA-TCB was tested in vivo in human CD34+ stem cell humanized NSG mice bearing subcutaneous human gastric adenocarcinoma MKN-45 or human pancreatic adenocarcinoma HPAFII xenografts." (PMID 41283511, 2025). "The histological examination showed a gastric adenocarcinoma with a synchronous GIST sized 2 cm and S-100, CD117, and CD34 positive." (PMID 24455386, 2013). "A series of 109 gastric adenocarcinoma cases that had undergone surgical resection was examined immunohistochemically using antibodies against VEGF-A, PDGF-B, and CD34, followed by further examination of PDGFR-β phosphorylation by immunoblotting analysis." (PMID 21118571, 2010). "Immunohistochemical analysis showed that these cells expressed cytokeratin 7 but not cytokeratin 20, CD117, CD34, chromogranin A, and synaptophysin, confirming the diagnosis of exophytic gastric adenocarcinoma with peritoneal dissemination." (PMID 42017098, 2026). "However, gastric adenocarcinomas do not provide a differential diagnostic problem, as they are most usually negative for KIT, DOG1, and CD34, while GISTs are usually positive for at least one of these markers." (PMID 35804982, 2022).
gastric tumor (9 papers, 2008 to 2024). "We identified all these cases, with CD34-positive or PAS-positive vascular channels containing erythrocytes formed by gastric tumor cells, as VM-positive structures." (PMID 30833656, 2019). "Our results also demonstrated that K5 significantly inhibited the expression of HIF-1α, VEGF, and CD34 in xenograft gastric tumours in mice and in SGC-7901 tumour cells." (PMID 29072683, 2017). "In the present study, we evaluated MVAs (CD34-immunopositive microvessel areas) in gastric tumor sections and the expressions of several angiogenic molecules to investigate angiogenesis." (PMID 21696576, 2011). "In particular, in gastric tumours, CD34, Desmin and Smooth Muscle Actin (SMA) were positive in 98%, 9% and 41% of the samples respectively; while in extra-gastric tumours, they were positive in 65%, 0% and 56% of the samples." (PMID 18474118, 2008). "Our data showed the involvement of CD31- or CD34-positive cancer cells in the formation of VM channels and parallel expression of CD31 and CD34 with tumor progression, thereby suggesting that CD31 and CD34 enhance the channel-forming ability of gastric tumor cells." (PMID 30833656, 2019). "Therefore, CD31 and CD34 may be therapeutic targets for preventing VM-mediated gastric tumor growth and metastasis." (PMID 30833656, 2019). "The gastric tumor demonstrated DOG1 and CD117 (KIT) positivity, with focal CD34 staining." (PMID 38538628, 2024). "We found that, unlike that of CD105, the analysis of the expression of CD31 and CD34 did not lead to a significant increased staining in gastric tumors, compared to the normal counterpart." (PMID 31263680, 2019). "Interestingly, we found that the luminal surface of gastric tumor cells that form VM channels showed PAS-positive reaction, and that the involvement of CD31/CD34-positive tumor cells in the formation of VM channels." (PMID 30833656, 2019).
hemoglobinopathies (9 papers, 2011 to 2025). "It is of considerable significance that vector pEPβ-globin is capable for gene transfer of the β-globin transgene into the CD34+ cells, the main target cells for gene therapy in the haemoglobinopathies." (PMID 37761914, 2023). "The study of β-globin gene expression in CFC assay colony cells provided excellent results for episomal gene delivery and was highly promising for all CD34+ cell-deriving diseases, primarily haemoglobinopathies." (PMID 37761914, 2023). "They compared their outcomes to a group of 40 patients with hemoglobinopathies who received CD34+-selected peripheral blood and bone marrow grafts (n = 32) or CD34+-selected peripheral blood and CD3+/CD19+-depleted bone marrow grafts (n = 8)." (PMID 36013014, 2022). "Gene therapy currently in development for hemoglobinopathies utilizes ex vivo lentiviral transduction of CD34+ hematopoietic stem and progenitor cells (HSPCs)." (PMID 29102562, 2018). "We determined that PGE2 increased the level of lentiviral transgene delivery in ex vivo culture for CD34+ cells derived from both healthy human donors and human donors with primary hemoglobinopathies." (PMID 29102562, 2018). "We investigated whether PGE2 could promote lentivirally mediated transduction, and increase transgenic hemoglobin protein expression, in primary CD34+ cells derived from patients with hemoglobinopathies." (PMID 29102562, 2018). "A significant increase in HbF levels in the erythroid cells derived from the CD34+ cells transduced with Ery-Lin-shBCL11A LVs suggests that this vector may be suitable for gene therapy applications for hemoglobinopathies after modifications to remove the selection markers." (PMID 35982069, 2022). "Thus, although our analysis has largely focused on gene therapy for hemoglobinopathies, we anticipate that PGE2 could find relevance in many further applications for gene modification in CD34+ cells beyond these indications." (PMID 29102562, 2018).
Hypercholesterolemia (9 papers, 2009 to 2022). An increased concentration of cholesterol in the blood. "We aimed to evaluate the effects of PCSK9 inhibitors (PCSK9-i) on CD34+CPCs and pulse wave velocity (PWV) in a cohort of heterozygous familial hypercholesterolemia (HeFH) subjects." (PMID 35885020, 2022). "PCR analysis showed that Tet1 deficiency and hypercholesterolemia did not change the expression of HSC markers, including CD34, Sca-1 and cKit." (PMID 32107419, 2020). "Following identical experimental conditions, FACS analysis revealed that juvenile rats had higher levels of cd45- [cd34+/kdr+]EPCs/ml than 4 m-old rats regardless of transgenic expression of human cholesteryl ester transfer protein, which induces significant hypercholesterolemia on regular rat chow." (PMID 23383116, 2013).
Hyperglycemia (9 papers, 2013 to 2025). An increased concentration of glucose in the blood. "Consistent with our in vitro model of hyperglycemia, CD34+ cells from CAD-T2DM patients displayed, a significant upregulation of CDKi p21 and p27 genes as well as upregulation of proinflammatory genes (IL6 and TNFα), and their transcription factor NFkB-p65." (PMID 38553774, 2024). "We have shown that metformin improves angiogenesis via affecting expression of growth factors/angiogenic inhibitors in CD34+ cells under hyperglycemia-hypoxia." (PMID 29351188, 2018). "Our recent work has shown that metformin improved angiogenesis by augmenting the expression of VEGFA and reducing angiogenic inhibitors in CD34+ cells under hyperglycemia-hypoxia." (PMID 29351188, 2018). "Metformin treatment of CD34+ cells under hyperglycemia led to differential expression of 65 genes compared with hyperglycemia alone." (PMID 26861446, 2016). "Indeed, CD34+ CB-HPC cultured on this vascular niche model in the presence of hyperglycemia generated less CFU-generating cells compared to normoglycemic conditions." (PMID 23555959, 2013). "EPC (CD144+/CD34+/VEGFR2+/CD14−/CD45−) were exposed to HG to mimic the hyperglycemia under diabetic conditions." (PMID 36497087, 2022). "However, the pro-angiogenic factor VEGFA was found to be significantly increased in CM collected from CD34+ cells treated with hyperglycemia (2.0-fold, p < 0.001) versus euglycemia, whereas no change was observed under hyperglycemia combined with hypoxia for 3 h versus hyperglycemia." (PMID 26861446, 2016). "We did not observe any direct effects of hyperglycemia on CD34+ CB-HPC survival or migratory function when these cells were kept in suspension overnight in the absence of endothelium (data not shown)." (PMID 23555959, 2013). "The CM from CD34+ cells treated with metformin displayed augmented levels of VEGFA either under euglycemia (1.6-fold, p = 0.008), euglycemia combined with hypoxia (1.4-fold, p = 0.037), and hyperglycemia combined with hypoxia (1.2-fold, p = 0.037) compared with the metformin-untreatedcondition." (PMID 26861446, 2016). "However the lack of effects after overnight exposure of CD34+ HPC to hyperglycemia in vitro, cannot fully rule out effects after sustained in vivo exposure." (PMID 23555959, 2013). "Hyperglycemia exerts also a negative impact on CD34+CD14+ and CD34+CD14- circulating proangiogenic cells by inhibiting the secretion of the angiogenic microRNA126 within exosomes." (PMID 30327618, 2018).
ischemic cardiomyopathy (9 papers, 2014 to 2023). Ischemic cardiomyopathy is a cardiomyopathy in which a weakness in the muscle of the heart due to inadequate oxygen delivery to the myocardium with coronary artery disease being the most common cause. "Vrtovec’s study utilizing transendocardial injection of CD34+ cells for the treatment of ischemic cardiomyopathy achieved an 8% improvement of LVEF (p < 0.001) and similar improvements in non-ischemic dilated cardiomyopathy." (PMID 37880753, 2023). "Currently, human CD34+ cells are being explored as a potential regenerative therapy for ischemic conditions, such as ischemic cardiomyopathy or peripheral ischemia, because this cell population includes endothelial progenitor cells." (PMID 27537262, 2016). "Among other cell lines, CD133+ and CD34+ cells were reported to reduce the CCS grades in patients with ischemic cardiomyopathy." (PMID 25000346, 2014). "Patients with ischemic cardiomyopathy (ICM) showed significantly lower CD34+KDR+ EPC levels when compared to non-ischemic dilated cardiomyopathy patients (DCM) (0.0010 ± 0.0007 vs 0.0030 ± 0.0024 cells/100 leukocytes, p = 0.032)." (PMID 32448383, 2020). "We performed a post hoc analysis of patients, enrolled in 2 prospective trials investigating the clinical effects of CD34+ cell therapy in patients with ischemic cardiomyopathy (ICMP) and nonischemic dilated cardiomyopathy (DCMP)." (PMID 31885743, 2019).
malignant fibrous histiocytoma (9 papers, 2010 to 2023). "Low mitotic rates, clusters of hyalinized thin-walled ectatic vessels, and immunoreactivity for CD34 help differentiate PHAT from malignant fibrous histiocytoma." (PMID 23420140, 2013). "Benign fibrous histiocytoma or low-grade malignant fibrous histiocytoma cells stain negative for S-100, CD34, and EMA, and stain positive for CD68." (PMID 24410763, 2014). "The presence of classic epithelioid cells with intracytoplasmic vacuoles in myxohyaline stroma and the positive expression of CD31 and CD34 can usually favor the correct diagnosis and rule out malignant fibrous histiocytoma." (PMID 23800015, 2013). "Malignant fibrous histiocytomas can occasionally be CD34 positive but are negative for CD99." (PMID 27044420, 2016).
myeloid sarcoma (9 papers, 2016 to 2026). A tumor mass composed of myeloblasts or immature myeloid cells. "Biopsy of the left inguinal lesion showed MPO positivity, CD34 positivity, partial TdT positivity, and a Ki-67 index of about 80%, supporting myeloid sarcoma." (PMID 42200007, 2026). "Histopathological examination with immunohistochemistry revealed tumor cells positive for myeloperoxidase and CD34 with a high Ki-67 proliferation index, confirming the diagnosis of multifocal myeloid sarcoma." (PMID 42051833, 2026). "In AML/myeloid sarcoma, MPO, CD117, CD33, CD34, and TdT are positively expressed but B- and T-lineage markers are negative." (PMID 39559598, 2024). "Our case was thought to be in favor of myeloid sarcoma, since MPO-, CD34-, CD117-, HLA-DR-, and LCA-positive immunoreactivity was detected in the tru-cut biopsy specimens performed from lesions showing FDG uptake in bilateral breasts and axillae." (PMID 34325712, 2021). "CD34, MPO, CD117, CD68, and lysozyme positivity also support the diagnosis of myeloid sarcoma." (PMID 33432557, 2021). "Flow cytometry showed an immature cell population (CD45 dim) that was negative for CD34, CD56, CD117, and MPO; strongly positive for CD4; and variably positive for CD10, CD33, HLA‐DR, CD68, CD123, and E‐cadherin, consistent with myeloid sarcoma (MS)." (PMID 31788302, 2019).
neuroepithelial tumors (9 papers, 2014 to 2025). "CD34 is also positive in several other low-grade epilepsy-associated neuroepithelial tumors (LEATs) such as gangliogliomas, DNETs, pleomorphic xanthoastrocytomas, and areas of focal cortical dysplasia." (PMID 40861626, 2025). "High expression of CD34 and DNA methylation has been found in children with neuroepithelial tumors." (PMID 33363022, 2020). "The proposed terms are: basic (oncofetal) neuroepithelial tumor “BNET” with CD34 expression, compared to a (predominant) gangliocytic neuroepithelial tumor “GNET” without CD34 expression." (PMID 24858213, 2014).
renal cell carcinoma (9 papers, 2007 to 2022). "We employed a method of automated, quantitative analysis of in situ tumor components to identify the area of CD-34 staining endothelial cells within renal cell carcinoma tumors." (PMID 23316728, 2013). "For renal cell cancer patients, two distinct CD34+ cell populations, which differ in the expression of the leucocyte marker CD45 and progenitor marker CD133, were identified in NSCLC patients." (PMID 20010948, 2010). "First, CD34, an endothelial progenitor biomarker, was discovered in renal cell carcinoma expressing MMP7, suggesting that MMP7 may contribute to tumourigenesis by correlating with tumour-induced neovascularization." (PMID 31937294, 2020). "The renal neoplastic cells failed to stain with antibodies against renal cell carcinoma marker (RCC) {Ventana}, S-100 protein (Ventana), chromogranin (Ventana), cytokeratins (AE1/AE3, 8/18, 7/20) {Ventana}, CD34 (Ventana), and myogenin (Ventana) {not shown}." (PMID 18053181, 2007). "Immunohistochemistry indicated FLI-1(+), CD99(+), Vimentin(+), CyclinD1(+), WT-1(+), EMA(+), Bcl2(-), Ki-67(+) 60%, CD56(-), CK(-), CD34(-), Desmin(-), and SMA(-), which suggested that renal clear cell sarcoma may not rule out renal cell carcinoma." (PMID 33859949, 2021).
T-cell acute lymphoblastic leukemia (9 papers, 2012 to 2025). Acute lymphoblastic leukemia of T-cell origin. "UL-1 was previously classified as a T cell lymphoma; however, based on expression of CD34, a surface glycoprotein expressed on hematopoietic stem cells, we suggest it is more representative of a T-cell acute leukemia (T-cell ALL)." (PMID 27639374, 2016).